RYR2 (ryanodine receptor 2)
Diseases named in the same sentence as RYR2 in open-access papers (continued):
Sharing a sentence is not in itself a finding about the gene and the disease.
heart failure (continued). "For example, in models of heart failure, it has been reported that over-expressing FKBP12.6 or introducing molecules of FKBP12.6 that may bind tighter to RyR2, have beneficial effects." (PMID 22363773, 2012). "Furthermore, the expression levels of RyR2 and FKBP12.6 were shown to be decreased in heart failure, while CaMKII expression was increased by 50–100%, and phosphorylation at PKA-specific sites was decreased and phosphorylation at CaMKII-specific sites was increased during this process." (PMID 36225189, 2022). "The essential role of CaM on the pathogenesis of heart failure was clearly shown by the finding that amino acid substitutions within a core CaM binding sequence in RyR2 (W3587A/L3591D/F3603A)} that disrupts CaM binding, indeed resulted in severe cardiac hypertrophy and early death in mutant mice." (PMID 33244105, 2020). "The current amplitude of the MG23 full-open state was consistent with that previously reported for RyR2 sub-conductance gating, suggesting that in heart failure in which Zn2+ levels are elevated, RyR2 channels do not gate in a sub-conductance state, but rather MG23-gating becomes more apparent." (PMID 28630041, 2017). "However, other features of the Cacna1c+/− model clearly differ from the Ca2+ handling remodeling in hypertrophy and heart failure, such as the increased expression of SERCA (decreased in heart failure) or the lack of altered phosphorylation of RyR2 at S2814 (increased in heart failure)." (PMID 37372947, 2023). "Therefore, the excessive activation of RyR2 may lead to the worsening of heart failure rather than improvement of cardiac function." (PMID 34639137, 2021).
Ventricular arrhythmia (84 papers, 2008 to 2026). "CPVT is the primary condition related to RYR2 mutations and is considered to be stress‐caused ventricular arrhythmias and SCD in hearts with normal structure." (PMID 41510139, 2026). "S-nitrosylation of caveolin-1 heightens the risk of ventricular arrhythmia, whereas S-nitrosylation of RyR2, SERCA2, S100-A1, and L-type Ca2+ channels supports cardiac rhythm stability." (PMID 40867518, 2025). "To date, over 150 distinct pathogenic RYR2 variants have been identified, all of which promote aberrant diastolic calcium leakage, thereby triggering delayed afterdepolarizations and fatal ventricular arrhythmias." (PMID 40843724, 2025). "Phase maps demonstrated abnormal re-entrant patterns associated with ventricular arrhythmias in overall cardiac electrical activity in RyR2-R2474S/+ hearts while WT hearts maintained normal conduction." (PMID 39697246, 2024). "Pathogenic variants in RYR2 lead to ventricular arrhythmias, and therefore, the proband and her mother were referred for evaluation and follow-up with cardiology." (PMID 38432637, 2024). "The ventricular arrhythmia with the RyR2 mutation can also occur with the loss-of-function mutation, which causes a decrease in the Ca2+ release during systole resulting in a gradual overload of Ca2+ in the SR." (PMID 39590361, 2024). "Ventricular arrhythmias caused by RBM20-associated abnormal splicing of ion channels genes such as RYR2 were also reported." (PMID 36198914, 2022). "Animal studies suggest that VTs in RyR2-CRDS arise secondary to substantial electrophysiological remodeling that increases the susceptibility to ventricular arrhythmias via early-afterdepolarization (EAD)-mediated re-entrant mechanism." (PMID 33825858, 2021). "It is generally believed that RyR2-associated ventricular arrhythmias (VAs) and SCD result from GOF defects of the RyR2 channel." (PMID 33825858, 2021). "Given these fundamental differences in their functional impact, the diagnosis and treatment strategies for ventricular arrhythmias associated with GOF or LOF RyR2 mutations would have to be different." (PMID 33825858, 2021). "IVF and SCD associated with loss of RyR2 function represents a new entity of ventricular arrhythmias distinct from CPVT." (PMID 33825858, 2021). "Different strategies and protocols will be required for the diagnosis and treatment of ventricular arrhythmias associated with enhanced or suppressed RyR2 function." (PMID 33825858, 2021). "In contrast, other studies have reported that enhancing Ca2+ fluxes between the SR and mitochondria using mitochondrial Ca2+ uptake enhancers is beneficial in preventing the appearance of ventricular arrhythmia associated with RyR2 dysfunction." (PMID 33585462, 2020). "The described clinical presentation of ACM due to RYR2 mutations is characterized by polymorphic and effort-induced ventricular arrhythmias and high risk of sudden cardiac death." (PMID 32878278, 2020). "Hyperphosphorylation of RyR2 at S2808 and S2814 is associated with ventricular arrhythmia and FKBP dissociation from RyR2." (PMID 31028179, 2019). "The class Ic anti-arrhythmic drug flecainide, commonly known as an inhibitor of membrane Na+ channels, has been shown to have clinical efficacy for preventing ventricular arrhythmias in CPVT patients carrying either Casq2 or RyR2 mutations." (PMID 31456692, 2019). "Mutations in the cardiac ryanodine receptor Ca2+ release channel (RyR2) can cause deadly ventricular arrhythmias and atrial fibrillation (AF)." (PMID 31028179, 2019). "An individual with CPVT harboring a novel mutation in the type 2 cardiac ryanodine receptor (RyR2) was identified whose persistent ventricular arrhythmias during β-blockade with nadolol were abolished during flecainide treatment." (PMID 27491078, 2016). "Recently, a novel RyR2 mutation H29D associated with ventricular arrhythmia at rest was found to enhance the activation of single RyR2 channels by diastolic levels of cytosolic Ca2+." (PMID 26405799, 2015).
Ventricular arrhythmia (continued). "We discuss novel cellular mechanisms that appear more suitable to explain ventricular arrhythmias due to RyR2 loss-of-function mutations." (PMID 25480325, 2015). "Persistent phosphorylation of RyR2 will also increase the propensity for spontaneous Ca2+ releases, another mechanism that could contribute to higher susceptibility to ventricular arrhythmias, cardiac arrest and SCD, especially in out-of-hospital setting." (PMID 41516391, 2026). "In this context, gene therapies that target RyR2 stabilization, CaMKII inhibition, or calmodulin modulation—originally developed for inherited ventricular arrhythmias—could also help reduce ventricular arrhythmias caused by structural heart disease." (PMID 40843724, 2025). "The purpose of this study was to assess whether adeno-associated virus type-9 (AAV9)-mediated somatic genome editing could prevent ventricular arrhythmias by removal of the mutant allele in mice that are heterozygous for Ryr2 variant p.Arg176Gln (R176Q/+)." (PMID 38464671, 2024). "Thus, ventricular arrhythmias associated with RyR2 LOF represents a significant portion of RyR2-linked arrhythmogenic disorders that are yet to be explored." (PMID 33825858, 2021). "These channels are involved in the control of RyR2 channels, and RyR2 channels may predispose the patient to ventricular arrhythmias and sudden death." (PMID 27738639, 2016). "In general ventricular arrhythmias are initiated and maintained by either focal (ectopic) or re-entry mechanisms, which have been linked to increased diastolic SR Ca2+ leak from RyR2 and subsequent activation of the Na+/Ca2+-exchanger (NCX) at the cellular level." (PMID 26617522, 2015). "In summary, in the present study, we have characterized the impact of a recently identified RyR2 mutation H29D that is thought to be associated with ventricular arrhythmia at rest using a number of biochemical, electrophysiological, and Ca2+ imaging techniques." (PMID 26405799, 2015). "In conclusion, we have shown here the proof of principle that intravenously administered dantrolene suppresses ventricular arrhythmias in the congenital RyR2 defect and that the location of the RyR2 mutation may affect the antiarrhythmic effect of this drug." (PMID 25955245, 2015). "For example, optical mapping was used to map ventricular arrhythmias caused by RYR2 mutations." (PMID 22912535, 2012). "S107 is another more selective rycal with demonstrated ability to protect against ventricular arrhythmias in a mouse model with a RyR2 gain-of-function mutation in addition to reversing the development of HF in a mouse model of constitutively phosphorylated RyR2." (PMID 32116711, 2020). "Gene-silencing strategies have been employed to selectively suppress pathogenic Ryr2 alleles in murine models of CPVT1, yielding significant suppression of ventricular arrhythmias." (PMID 40843724, 2025). "The mechanisms by which defective RyR2 channels lead to ventricular arrhythmias in CPVT remain incompletely understood." (PMID 39697246, 2024). "Heterozygous, RyR2-R2474S/+, mice exhibited exercise-induced ventricular arrhythmias and sudden cardiac death recapitulating clinical CPVT." (PMID 39697246, 2024). "Heterozygous CPVT mutant RyR2-R2474S mice exhibit exercise-induced ventricular arrhythmias, and sudden cardiac death, which can be prevented by treatment of the mice with Rycals." (PMID 36647824, 2023). "The timely opening and closing of type 2 ryanodine receptor (RyR2) is critical for ensuring rhythmic cardiac contraction–relaxation cycles, and the disruption of these processes can elicit Ca2+ waves, ventricular arrhythmias, and SCD." (PMID 36613717, 2022). "Researchers have found that ADRB2 strongly increases localized RyR2-related cAMP levels during the over-activation of the SNS associated with cardiac hypertrophy or HF and increases ventricular arrhythmias." (PMID 35498046, 2022).
Ventricular arrhythmia (continued). "In present study, we explored the mechanism of CHSSC ameliorates ventricular arrhythmia following myocardial ischemia via inhibiting the CaMKII/FKBP12.6/RyR2/Ca2+ signaling pathway." (PMID 36225189, 2022). "It has become imperative to identify patients with RyR2 LOF mutations, as their phenotypes are effectively concealed prior to their onset of ventricular arrhythmias or sudden death." (PMID 33825858, 2021). "Abnormal RyR2-mediated Ca2+ release from the SR can lead to both atrial and ventricular arrhythmias, some primary arrhythmia disorders including CPVT and forms of acquired arrhythmias associated with heart disease (AF during HF)." (PMID 33013458, 2020). "As a result, mutant RYR2 proteins fail to retain Ca2+ in the SR-enhancing spontaneous release of Ca2+ which leads to delayed after-depolarizations (DADs) and ventricular arrhythmia in ACM patients." (PMID 32878278, 2020). "It is, therefore, predictable that the RYR2 mutations observed in ARVD2 patients enhance Ca2+ leakage and increase spontaneous SR Ca2+ release, thereby leading to DADs and ventricular arrhythmia." (PMID 31426283, 2019). "Protein glycosylation and oxidized CaMKII are significantly up-regulated in the DCM, therefore CaMKII activation and RyR2 phosphorylation has been proposed as a potential mechanism of heart failure, ventricular arrhythmias and apoptosis in this disease." (PMID 32038301, 2019). "miR-1 and miR-133 affect the ryanodine-receptor-2 (RyR2) through their action on B56α and PP2A, which results in RyR2 hyperphosphorylation, increasing the spontaneous Ca2+ spark frequency and ventricular arrhythmia risk." (PMID 31052231, 2019). "Abnormal gating of ryanodine receptors (RyR2), the calcium release channels of the sarcoplasmic reticulum, can produce ventricular arrhythmias." (PMID 29439404, 2018). "Our results suggest that HFD increases the activity of RyR2 channels via a redox-dependent mechanism, favoring the appearance of ventricular arrhythmias." (PMID 29439404, 2018). "High-fat-diet-induced obesity increases the occurrence of ventricular arrhythmias and favors the increased responses of RyR2 channels to cytoplasmic Ca2+ concentration." (PMID 29439404, 2018). "SERCA2a gene transfer in a HF model led to the reduction of Ca2+ alternans, reduced RyR2 phosphorylation and the reduced inducibility of ventricular arrhythmias." (PMID 26818679, 2016). "ARVD2, caused by mutations in the ryanodine receptor (RyR2), is clinically different from other forms of ARVD/C in that ventricular arrhythmias are stereotypically effort-induced." (PMID 19440513, 2008). "For example, the targeted silencing of the ryanodine receptor 2 (RYR2) gene mutation can reduce the expression level of the R4496C mutant RYR2 protein, increase the wild-type expression level, and reduce the incidence of ventricular arrhythmia induced by isoproterenol." (PMID 39596569, 2024). "RYR2 is an ion channel that plays a crucial role in Ca2+ release from the myocardial sarcoplasmic reticulum, whose dysfunction or aberrant expression can lead to fatal ventricular arrhythmia and SCD." (PMID 37600027, 2023). "CHSSC may reduce the incidence of ventricular arrhythmias following myocardial ischemia through inhibition of the CaMKII/RyR2/FKBP12.6/Ca2+ signaling pathway." (PMID 36225189, 2022). "Chronic PKA phosphorylation of RyR2 at Ser2808 results in depletion of Calstabin2 and SR Ca2+ leakage, which is one of the earliest described pathological mechanisms of Ca2+ leakage that contributes to ventricular arrhythmias." (PMID 36225189, 2022). "Both RYR2 and CASQ2 mutations cause spontaneous premature SR Ca releases in ventricular myocytes that facilitate the generation of delayed afterdepolarizations (DADs) and focal ventricular arrhythmias." (PMID 34990403, 2022).
Ventricular arrhythmia (continued). "Cardiac ryanodine receptor (RYR2) gene mediates the release of diastolic calcium from the sarcoplasmic reticulum that is required for myocardial contraction.Changes in this gene can trigger life-threatening ventricular arrhythmias and sudden cardiac death." (PMID 34393635, 2021). "In particular, one study showed that LCACs oxidize RyR2, resulting in increased SR Ca2+ leak, thereby providing a direct link to ventricular arrhythmias, although the underlying mechanism has not been elucidated." (PMID 34200203, 2021). "Increases in RyR2 content or phosphorylation status could account for the ventricular arrhythmias observed in HFD-fed mice and the increased activity observed in isolated channels." (PMID 29439404, 2018). "In this study, we hypothesized that inhibition of Rac1 protects against ventricular arrhythmia during myocardial I/R through decreases in ROS, RyR2 oxidation and SOICR." (PMID 27222313, 2016). "Therefore, PKA activity and RyR2 phosphorylation is subsequently upregulated, leading to ventricular arrhythmias." (PMID 27966586, 2016). "In this study, we investigated whether these two polymorphisms (RyR2-Q2958R and HRC-S96A) are associated with the occurrence of spontaneous ventricular arrhythmias in patients receiving an ICD for primary and secondary prevention of SCD." (PMID 26904356, 2016). "We tested 35 Kazakhstani patients with episodes of ventricular arrhythmia, two of those with classical CPVT characteristics and 33 patients with monomorphic idiopathic ventricular arrhythmia, for variants in the hot-spot regions of the RYR2 gene." (PMID 24978818, 2014). "Specifically, mutations in the RyR2 and CASQ2 genes lead to a leakage of Ca2+ from the SR in diastole, particularly under adrenergic stress (exercise, emotional stress), resulting in delayed after-depolarizations and therefore vulnerable to ventricular arrhythmias." (PMID 31380394, 2019). "However unlike RYR1/RYR3, RYR2 is expressed mainly in cardiac muscle tissue and deleterious RYR2 mutations are associated with ventricular arrhythmias." (PMID 31861911, 2019). "Six further rare missense variants have been identified in RYR2, mapping the locus to chromosome 1q42‒q43 in four independent families with the same clinical manifestations and close to CPVT based on exercise-induced ventricular arrhythmias, high penetrance, and a 1:1 sex ratio." (PMID 31426283, 2019). "Since the recognition of RyR2 as a gene responsible for CPVT, functional analyses have suggested that DADs following Ca2+ leakage from the sarcoplasmic reticulum (SR) are associated with ventricular arrhythmia in CPVT; however, the mechanisms underlying SR Ca2+ leak have not been elucidated." (PMID 27764147, 2016). "Although still under debate if hyperactivated PKA or CaMKII play the major role for increased RyR2 activation and subsequent SR Ca2+ leak, it is common sense that β-adrenoceptor stimulation is the general trigger for SR Ca2+ leak in both atrial and ventricular arrhythmias." (PMID 26617522, 2015). "We also reported that the DKO mice developed more severe ventricular arrhythmias than the CASQ2−/− mice, thus, suggesting aggravated RyR2 dysfunction." (PMID 36672139, 2023). "We showed that the new RyR2 variant in SPRY1 domain affects the channel structure and function and proposed that the cardiac electrical instability of this patient leading to lethal ventricular arrhythmias could be due to the combined effects of at least two of these variants." (PMID 33664309, 2021). "This factor exerts intrinsic negative regulation of the RyR2 and disrupts the RyR2-FKBP interaction, resulting in SR Ca2+ leakage and atrial and ventricular arrhythmias." (PMID 33585462, 2020). "Our study suggests that Rac1 activation contributes to RyR2 oxidation, SOICR and ventricular arrhythmia during myocardial I/R." (PMID 27222313, 2016).
Ventricular arrhythmia (continued). "Because increased RYR2 activity and spontaneous diastolic Ca release is an accepted cellular mechanism for the generation of ectopic ventricular beats, CPVT can be considered a model to study Ca-triggered ventricular arrhythmia." (PMID 34990403, 2022). "Subsequently, compound S107, an orally available 1,4-benzothiazepine derivative with high potency on RyR2 and no significant off-target effects, was shown to suppress ventricular arrhythmias in a RyR2 R2474S knock-in mouse model." (PMID 35677449, 2022). "Caveolin-3 overexpression could lead to the reduced diastolic spontaneous Ca2+ waves by inhibiting the hyperphosphorylation of ryanodine receptor-2 (RyR2) at Ser2814, thus leading to the abnormal LTCC current-induced ventricular arrhythmias." (PMID 35329921, 2022). "The increase in RyR2 activity shown here is an early event induced by the HFD, that may have a role, not only in the generation of ventricular arrhythmias suggested here, but also in the long-term generation of cardiac hypertrophy induced by HFD." (PMID 29439404, 2018). "Also, ventricular myocytes exhibit cardiac arrhythmogenic events leading to ventricular arrhythmias which can be prevented in transgenic mice expressing the CaMKII inhibitor AIP targeted to the SR membranes, avoiding phosphorylation of SR proteins (PLN and RyR2) by CaMKII (SR-AIP mice)." (PMID 32038301, 2019).